ATF4 (activating transcription factor 4)
Diseases named in the same sentence as ATF4 in open-access papers (continued):
Sharing a sentence is not in itself a finding about the gene and the disease.
asbestosis (2 papers, 2025). A lung disorder caused by inhalation of asbestos fibers. "In lung macrophages from individuals with asbestosis, ATF4 directly binds the PGC-1α promoter, driving mitochondrial biogenesis and respiration." (PMID 41529526, 2025).
autoimmune disease (2 papers, 2011 to 2018). A disorder resulting from loss of function or tissue destruction of an organ or multiple organs, arising from humoral or cellular immune responses of the individual to their own tissue constituents. "It has already been reported that HF activation of the Atf4/ISR via AAR stimulation is sufficient to explain HF biological effects in T-cells, and in turn HF-dependent amelioration of autoimmune disease." (PMID 21974968, 2011).
brain hemorrhage (2 papers, 2021 to 2025). "Therefore, LEF1, BLVRB, ITGAX and ATF4 are expected to become new biomarkers for intracranial hemorrhage." (PMID 40933575, 2025). "It has been shown that ATF4 increases the expression of transcriptional activator CHOP (DDIT3) and caspase-12, which promote apoptosis and reduce neuronal survival after brain hemorrhage." (PMID 34163322, 2021).
Cachexia (2 papers, 2018 to 2025). Severe weight loss, wasting of muscle, loss of appetite, and general debility related to a chronic disease. "In this study, we found that autophagy was upregulated in the livers of C26 mice as early as the pre-Cx stage, an effect that was enhanced at the onset of cachexia, with upregulation of ATF4-target autophagy genes." (PMID 40124481, 2025). "At the onset of cachexia, rpS6 and eIF2α signalings were concomitantly activated in the liver, with increased expression of activating transcription factor 4 (ATF4) target genes involved in amino acid synthesis and transport, as well as autophagy." (PMID 40124481, 2025). "In our study, we show that expression of ATF4-regulated genes involved in amino acid transport, amino acid synthesis and autophagy was clearly increased at the onset of cachexia, suggesting a role of ATF4 in promoting amino acid availability in the liver." (PMID 40124481, 2025). "Data from the present study highlight early cancer-related alterations in protein/amino acid homeostasis and activation of mechanisms regulating protein/amino acid metabolism in spleen and liver during progression to cachexia, likely involving the eIF2α-ATF4 signaling pathway." (PMID 40124481, 2025). "Nevertheless, the hepatic UPR markers GRP78 and ATF4 correlated positively with the change in body mass (the last 2 days of the experiment) and ATF4 correlated negatively with the tumor mass, suggesting that also some of the hepatic UPR indicators may be associated with the severity of cachexia." (PMID 30713500, 2018).
calcific aortic valve disease (2 papers, 2023 to 2024). "In this study we sought to analyze the critical role of oxidized phospholipid (OxPL) in the progression of calcific aortic valve disease (CAVD) with the involvement of activating transcription factor 4 (ATF4)." (PMID 37462732, 2023). "Expression of ATF4 was examined in mouse models of aortic valve calcification (AVC) induced by the high cholesterol (HC) diet." (PMID 37462732, 2023).
cerebral infarction (2 papers, 2021 to 2022). An ischemic condition of the brain, producing a persistent focal neurological deficit in the area of distribution of the cerebral arteries. "Overexpressed ATF4 reduced cerebral infarction volume, lowered neurological score and improves HE and Nissl staining." (PMID 34408630, 2021). "The silencing of ATF4 gave rise to the disappearance of the neuroprotective effects where the volume of cerebral infarction decreases and the absorption rate of glucose in ischemic tissue increases induced by tunicamycin and thapsigargin." (PMID 34408630, 2021).
chondrodysplasia (2 papers, 2021 to 2023). "In a model of metaphyseal chondrodysplasia type Schmid, a chondrodysplasia characterized by short stature and ER stress in the growth plate because of Col10a1 mutations, mice exhibit short stature because of increased expression of Sox9 via ATF4 and CHOP transactivation." (PMID 37796615, 2023). "Contribution to PERK/ATF4‐associated ISR and Chondrodysplasia." (PMID 33682108, 2021).
chordoma (2 papers, 2019 to 2025). Chordomas are rare malignant tumors arising from embryonic remnants of the notochord in axial skeleton. "In this study, we find that Doxo or Irino induce a moderate UPR in chordoma cells as shown by an increased expression of CHOP, BiP, ATF4, ATF6, and XBP1-s." (PMID 31767864, 2019).
congenital cataracts (2 papers, 2015 to 2025). "Accordingly, we detected the protein expression of p-eIF2α and the mRNA level of ATF4 in the lens of age-related, HM-related and congenital cataracts, which could represent the activation of the PERK/eIF2α/ATF4 pathway." (PMID 26091066, 2015).
coronary artery disease (2 papers, 2022 to 2026). "VPO1 and ATF4 might be potential biomarkers associated with coronary artery disease, especially in the follow-up and monitoring of treatment protocols, in addition to traditional risk factors." (PMID 36381079, 2022).
Crohn disease (2 papers, 2018 to 2025). A gastrointestinal disorder characterized by chronic inflammation involving all layers of the intestinal wall, noncaseating granulomas affecting the intestinal wall and regional lymph nodes, and transmural fibrosis. "Adherent-invasive Escherichia coli (AIEC), which is abnormally abundant in the intestinal mucosa of Crohn’s disease patients, also induces phosphorylation of GCN2 with subsequent eIF2α phosphorylation and increased ATF4 levels." (PMID 29930559, 2018). "By integrating multi-omics approaches, this study reveals a crucial connection between ferroptosis and immune microenvironment dysregulation in Crohn’s disease (CD), identifying seven hub ferroptosis-related differentially expressed genes (FEDGs): SCD, ATF4, SAT1, RPL8, MUC1, MTDH, and ATP6V1G2." (PMID 41515900, 2025).
cutaneous melanoma (2 papers, 2022). A primary melanoma arising from atypical melanocytes in the skin. "In contrast, ATF4 (activating transcription factor 4), and JUN, which both integrate stress signals, repress MITF expression and trigger cutaneous melanoma cell dedifferentiation." (PMID 35682684, 2022). "TNFα can also activate ATF4 and JUN, resulting in dedifferentiated cutaneous melanoma cells." (PMID 35682684, 2022).
cutaneous squamous cell carcinoma (2 papers, 2025). "In cutaneous squamous cell carcinoma (CSCC), METTL1 stabilizes Activating Transcription Factor 4 (ATF4) mRNA and increases its expression via m7G methylation." (PMID 40809384, 2025).
dementia (2 papers, 2022 to 2024). Loss of intellectual abilities interfering with an individual's social and occupational functions. "Meanwhile, a high ATF4 and PINK1 concentrations were observed in serious memory status in terms of clinical dementia rating (CDR) scores." (PMID 39394148, 2024). "Que exhibited a potential to alleviate the level of mammalian activating transcription factor 4 (ATF4), an element of the ISR, increased in this model of rodent dementia." (PMID 35455082, 2022).
Dystonia (2 papers, 2014 to 2018). An abnormally increased muscular tone that causes fixed abnormal postures. "Coding variants in ATF4, a direct target of eIF2α, were found in patients with focal dystonia and lastly, a recent gene-expression analysis in adult cerebellar tissue from a mouse model of DYT11 dystonia also identified genes associated with protein translation among the top down-regulated mRNAs." (PMID 29364887, 2018).
endometriosis (2 papers, 2020 to 2025). The growth of functional endometrial tissue in anatomic sites outside the uterine body. "Ferroptosis in endometriosis adversely affects gametes but is advantageous for combating lesions, requiring targeted approaches that inhibit ATF4 xCT in lesions while safeguarding follicles." (PMID 41226419, 2025). "So was our study, ATF4 had a higher level in the fertile than infertile patients with endometriosis." (PMID 33490107, 2020). "In endometriosis, a paradoxical equilibrium exists: granulosa cells undergo ferroptosis owing to iron-laden follicular fluid, whilst ectopic stromal cells persist by elevating ATF4-xCT levels." (PMID 41226419, 2025). "From the research, we could assume that the high expression of ATF4 might play a role in inhibiting the proliferation of endometriosis." (PMID 33490107, 2020).
gastric tumors (2 papers, 2012 to 2023). "Moreover, ATF4 is a valid target in drug-resistant gastric tumors, and developing effective inhibitors of ATF4 should be taken into consideration in the future." (PMID 22363646, 2012).
HCMV infection (2 papers, 2021). "However, we detected only minor and transient changes in eIF-2α phosphorylation during HCMV infection upon treatment with 1E7-03 or downstream ATF-4 upregulation." (PMID 34335531, 2021). "HCMV infection increases PERK protein levels and activity, as measured by autophosphorylation and ATF4 protein levels." (PMID 33947752, 2021).
head and neck cancer (2 papers, 2022 to 2025). A primary or metastatic malignant neoplasm affecting the head and neck.
hemorrhagic stroke (2 papers, 2022 to 2023). A stroke caused by a bleed on the brain. "Such ATF4 regulation can be targeted for neuroprotection with the CNS-permeable drug adaptaquin which attenuated ATF4-mediated gene expression and neurodegeneration in a mouse model of hemorrhagic stroke." (PMID 36359735, 2022).
hepatoblastoma (2 papers, 2013 to 2024). Hepatoblastoma (HB) is a malignant hepatic tumor and is the most common pediatric liver cancer. "Reduced LATS2 expression promotes hepatoblastoma progression by inhibiting ferroptosis through the YAP1/ATF4/PSAT1 axis." (PMID 39247829, 2024). "In conclusion, the AhR pathway, which involves ATF4, induces VEGF expression in glucose-deprived human hepatoblastoma HepG2 cells." (PMID 24330582, 2013).
HIV-1 infection (2 papers, 2024 to 2025). The type species of lentivirus and the etiologic agent of acquired immunodeficiency syndrome (AIDS). "The potential control of ATF4 by the new eIF2α kinases needs further investigation during HIV-1 infection." (PMID 38534416, 2024). "Despite the obvious link between ATF4 and autophagy, the role of ATF4 in autophagy in the context of HIV-1 infection remains poorly documented." (PMID 38534416, 2024). "In this review, we provide an overview of ATF4 functions during HIV-1 infection and explore the role of some of the poorly characterized ATF4 transcriptional targets that are involved in cell death, autophagy, metabolism, or in the immune response." (PMID 38534416, 2024). "Of interest, the induction of ATF4 following HIV-1 infection has been observed in several in vitro models." (PMID 38534416, 2024). "The role of ATF4 in autophagy and apoptosis is explored as in the context of HIV-1 infection programmed cell deaths contribute to the depletion of CD4 T cells." (PMID 38534416, 2024). "In this review, we focus specifically on ATF4-mediated signaling during human immunodeficiency virus 1 (HIV-1) infection and examine the multifaceted role of ATF4 in this context." (PMID 38534416, 2024). "While ATF4 levels have been shown to be increased by human immunodeficiency virus-1 (HIV-1) infection and to promote viral replication, data concerning the implementation of this regulation remain scarce." (PMID 38534416, 2024). "The induction of ATF4 during HIV-1 infection raises the possibility that ATF4 may play a role in viral replication." (PMID 38534416, 2024). "However, the role of ATF4 in regulating the death of CD4+ T cells in the context of HIV-1-infection has been poorly explored." (PMID 38534416, 2024). "This last point is less understood, and advances in our knowledge of the impact of post-translational modifications, particularly on the choice of ATF4 heterodimerization partners, should be decisive in understanding the control of ATF4 activity in the context of HIV-1 infection." (PMID 38534416, 2024). "To conclude, PERK and GCN2 may lead to ATF4 activation after HIV-1 infection, and the direct interaction of HIV-1 components with GCN2 and MARK2 may in turn control their ability to activate ATF4." (PMID 38534416, 2024). "This article aims to provide an overview of the role of ATF4 in HIV-1 infection." (PMID 38534416, 2024). "Given the limited data available, further investigations are needed to determine whether TMBIM5 plays a role in the induction of apoptosis downstream of ATF4 in response to HIV-1 infection." (PMID 38534416, 2024). "Taken together, these results suggest that the induction of ATF4 observed in CD4+ T lymphocytes during HIV-1 infection may contribute to the increased production of energy and amino acids required for viral replication." (PMID 38534416, 2024). "Therefore, it can be hypothesized that ER stress induced by HIV-1 infections could activate ATF4 and regulate TLR2 gene expression in infected cells." (PMID 38534416, 2024). "ATF4 also mediates TLR4-triggered cytokine production, and it has been shown that the level of TLR4 is increased upon HIV-1 infection." (PMID 38534416, 2024). "We summarize models in which ATF4 activation has been reported during HIV-1 infection and focus on how HIV-1 can induce ATF4 activation." (PMID 38534416, 2024). "We finally discuss the putative role of the ATF4 paralogue, named ATF5, in HIV-1 infection." (PMID 38534416, 2024). "To date, ATF4 activation in the context of HIV-1 infection has not been reported to originate from mitochondrial stress." (PMID 38534416, 2024). "While PERK is one of the sensors of the UPR with IRE-1 and ATF6, the functional role of PERK in ATF4 induction in response to HIV-1 infection is not fully demonstrated." (PMID 38534416, 2024).
HIV-1 infection (continued). "While PKR contributes to ATF4 translation in response to endoplasmic reticulum (ER) stress, paradoxically, to our knowledge, no study reports the induction of ATF4 in the context of HIV-1 infection through an endogenous PKR/eIF2α pathway." (PMID 38534416, 2024).
Hyperinsulinemia (2 papers, 2017 to 2025). An increased concentration of insulin in the blood. "Insulin pretreatment essentially abrogated the ability of IGF1 to regulate Atf4, Agrp, and Pomc, suggesting that hyperinsulinemia induced IGF1 resistance in hypothalamic neurons." (PMID 40105689, 2025). "Thus, the experimental HFD setup used in our study resulted in hyperinsulinemia and hepatosteatosis associated with specific changes in enhancer activity and gene transcription likely regulated by transcription factors such as SREBP, ATF-4 and C/EBP." (PMID 28071704, 2017).
hyperthyroidism (2 papers, 2017 to 2025). Overactivity of the thyroid gland resulting in overproduction of thyroid hormone and increased metabolic rate. "In summary, this study demonstrates that hyperthyroidism induces oxidative stress in GCs, which triggers endoplasmic reticulum stress via the eIF2α/ATF4 pathway and leads to apoptosis." (PMID 41008998, 2025). "In the present study, treatment with 100 mg/kg EGCG significantly reduced the expression of p-eIF2α, ATF4, CHOP, and Caspase-3, confirming its efficacy in alleviating hyperthyroidism-induced ovarian ERS and suppressing apoptosis." (PMID 41008998, 2025). "In the present study, we demonstrated that hyperthyroidism induces OS, which subsequently triggers ERS via the GRP78/eIF2α/ATF4 pathway, ultimately promoting granulosa cell (GC) apoptosis." (PMID 41008998, 2025).
insulinoma (2 papers, 2017 to 2022). "Time-dependent changes in ATF4 expression and the effects of Gsk-3 inhibition were examined in mouse insulinoma cells similarly incubated with tunicamycin." (PMID 36362372, 2022). "The levels of XBP-1(u), XBP-1(s), PUMA, and ATF4 mRNA were similar or slightly elevated in islets relative to insulinoma cells." (PMID 28212395, 2017).
lactic acidosis (2 papers, 2021 to 2023). Metabolic acidosis characterized by the accumulation of lactate in the body. "For example, ATF4 upregulation confers the survival of amino acid deprivation, combined hypoxia and lactic acidosis, and various tumor therapeutics." (PMID 34294679, 2021).
lung disease (2 papers, 2022). "Despite being less studied in lung disease, ATF4 was a profibrotic role in lung fibroblast activation and renal tubulointerstitial fibrosis." (PMID 36555349, 2022).
metastatic cancer (2 papers, 2016 to 2021). A carcinoma which has spread from the original site of growth to another anatomic site. "First, circulating metastatic cancer cells have increased level of ATF4." (PMID 27802179, 2016).
metastatic melanoma (2 papers, 2020 to 2025). A melanoma that has spread from its primary site to another anatomic site. "In a study, NLRP1 operates as a downstream effector of MAPK/ERK signaling via activating transcription factor 4 (ATF4) in metastatic melanoma cells, where ATF4 directly regulates NLRP1." (PMID 40872623, 2025). "Here, we report that NLRP1 is a downstream effector of MAPK/ERK signaling through the activating transcription factor 4 (ATF4), creating regulation in metastatic melanoma cells." (PMID 33396632, 2020).
metastatic tumor (2 papers, 2014 to 2023). "Finally, IHC staining analyses further confirmed the higher ATF4 expression in metastatic tumors from cytotoxin‐treated 4TO7‐Luc and HeLa‐Luc NDCs." (PMID 36739602, 2023). "To investigate whether MMP-2 and MMP-7 were up-regulated by ATF4 in vivo, we performed immunohistochemistry in the metastatic tumors that had been injected with the TE-1LM-ATF4, TE-1HM-SCR, and TE-1HM-siATF4 cells." (PMID 25078779, 2014).
microcephaly (2 papers, 2019 to 2020). A congenital or acquired developmental disorder in which the circumference of the head is smaller than normal for the person's age and sex. "Interestingly, while mutations in ATF4 have not been reported in human pathology, forced expression of the gene in Xenopus embryos resulted in severe microcephaly with absence of eyes." (PMID 31832602, 2019). "CRISPR/Cas9 disruption of these genes recapitulated the microcephaly in mice and zebrafish and knockdown of OSGEP, TP53RK, TPRKN resulted in impaired protein translation, ER stress and the activation of the PERK-eIF2α-ATF4 and IRE1α-XBP1 pathways." (PMID 31832602, 2019).
multiple sclerosis (2 papers, 2013 to 2022). A progressive autoimmune disorder affecting the central nervous system resulting in demyelination. "Our and other studies have demonstrated upregulation of ER stress markers CHOP, BiP, ATF4, XBP1 and phosphorylated e-IF2 alpha (p-eIF2 alpha) in biopsy and post-mortem human multiple sclerosis (MS) samples." (PMID 24252779, 2013). "LW-213, a derivative of WGI, was reported to modulate eIF-2α/ATF4/CHOP axis in human cutaneous T-cell, and given the fact that WGI could pass the blood brain barrier to regulate eIF-2α/ATF4/CHOP in neurons, it is likely to ameliorate multiple sclerosis via inhibiting caspase-11." (PMID 36188625, 2022).
Myocardial fibrosis (2 papers, 2020 to 2025). "Hyperactivation of the ATF4/TGF-β1 signaling axis is associated with myocardial fibrosis in ARVC, representing a potential therapeutic target." (PMID 40989111, 2025). "Mechanistically, DSG2 knock-in mice exhibit myocardial fibrosis and heart failure phenotypes with pronounced PERK/ATF4 pathway activation and TGF-β1 upregulation." (PMID 40989111, 2025). "Myocardial fibrosis was also elevated in cardiac tissue of SIRT3 knockout mice, as reported in other studies, and consistent with this, the expression of TGF-β, ATF4, and EDN-1 was inhibited by SIRT3 overexpression in AC16 cells and in neonatal rat cardiomyocytes." (PMID 32296036, 2020).
nonalcoholic fatty liver (2 papers, 2018 to 2021). "For example, in human liver cells, lipotoxicity can induce apoptosis via the PERK/ATF4/CHOP signaling pathway, which might be one of the pathogeneses of nonalcoholic fatty liver." (PMID 33943005, 2021).